PBX3 (PBX homeobox 3)
Diseases named in the same sentence as PBX3 in open-access papers (continued):
Sharing a sentence is not in itself a finding about the gene and the disease.
PBX3 also shares sentences with these, for which no sentence is quoted: leiomyoma (2 papers); multiple myeloma (2); osteosarcoma (2); acute leukemia (1); acute lymphocyte leukemia (1); celiac disease (1); cerebral artery occlusion (1); colorectal tumors (1); dental caries (1); dental disorder (1); esophageal squamous cell carcinoma (1); Ewing sarcoma (1); Fanconi anemia (1); hepatoblastoma (1); laryngeal squamous cell carcinoma (1); nasopharyngeal carcinoma (1); non-small cell lung carcinoma (1); oligoastrocytoma (1); oligodendroglioma (1); orofacial clefting (1); periodontitis (1); prostatic adenocarcinoma (1); rectal cancer (1); renal carcinoma (1); retinoblastoma (1); rhabdomyosarcoma (1); sarcoma (1); schizophrenia (1); schwannoma (1); thyroid cancer (1).
A further 2 diseases each share a sentence with PBX3 in 1 paper.